AKT1 (AKT serine/threonine kinase 1)
Diseases named in the same sentence as AKT1 in open-access papers (continued):
Sharing a sentence is not in itself a finding about the gene and the disease.
Chordoid Meningioma (2 papers, 2020 to 2022). A WHO grade II, usually recurring meningioma characterized by the predominance of tissues that are histologically similar to chordoma. "Genetically, previous studies found that chordoid meningiomas had sparce NF2, TRAF7, KLF4, SMO, AKT1 and SMARCB1 mutations common to non-chordoid meningioma." (PMID 35440040, 2022). "Together, the mutations in TRAF7, KLF4, AKT1, and VHL genes were mutually exclusive and occurred in 64.7% of the well-differentiated chordoid meningiomas from ED group #3." (PMID 31963394, 2020). "Chordoid meningiomas were enriched in mutations in chromatin remodeling genes EP400 (8/11,73%) KMT2C (4/11, 36%) and KMT2D (4/11, 36%), and showed low or absent NF2, TERT, SMO, and AKT1 mutations." (PMID 35440040, 2022).
co-infection (2 papers, 2011 to 2025). "Subsequently, we obtained the top 16 hub targets of probenecid for SARS-CoV-2/RSV co-infection, namely, AKT1, ALB, EGFR, CASP3, CTNNB1, SRC, HSP90AA1, and so on." (PMID 40371107, 2025).
colorectal adenoma (2 papers, 2016 to 2021). An adenoma that arises from the colon or rectum.
Constipation (2 papers, 2022 to 2025). Infrequent or difficult evacuation of feces. "Furthermore, the network pharmacology analysis showed that Akt1, Stat3, Mapk8, Hsp90aa1, Cat, Alb, Icam1, Sod2, and Gsk3b can be regarded as the core anti-constipation targets." (PMID 35408632, 2022).
endometrioid adenocarcinoma (2 papers, 2021). An adenocarcinoma characterized by the presence of malignant glandular epithelial cells resembling endometrial cells. "Previous reports have suggested that activation of the PI3K/AKT pathway is involved in the development of endometrioid adenocarcinoma, and that atypical hyperplasia is also associated with AKT1 mutations, leading to benign and (pre) malignant endometrial lesions." (PMID 34670536, 2021). "AKT1 actionability was 22, 45 and 35% in patients with high-grade serous, endometrioid and clear cell carcinomas, respectively, and AKT1 alterations were observed in 14–18% of patients with serous and endometrioid carcinomas." (PMID 33947352, 2021).
enteritis (2 papers, 2023 to 2025). Inflammation of the small intestine. "The results indicated that the inhibitory effect of Homo on enteritis was closely associated with RLN, MAPK, TNF, AKT1, and CASP3 signaling pathways." (PMID 40529132, 2025). "The four main active compounds of MCE involved in the treatment of enteritis are SAN, CHE, PRO, and ALL, and the five core targets are HSP90AA1, MAPK1, HRAS, JAK2, and AKT1." (PMID 37200837, 2023). "Five core targets including mitogen-activated protein kinase 1 (MAPK1) and AKT serine/threonine kinase 1 (AKT1) were obtained using the PPI network, which are considered the potential targets for the four active compounds of MCE in the treatment of enteritis." (PMID 37200837, 2023).
essential hypertension (2 papers, 2022 to 2024). Hypertension that presents without an identifiable cause. "Among them, AGTR1, AKT1 with puerarin, EDNRA with tanshinone IIA, MAPK14 with daidzein, MAPK8 with ursolic acid, and CHRM2 with cryptotanshinone all have a strong correlation with GJD in the treatment of primary hypertension." (PMID 36046450, 2022). "The research uncovered that the key active ingredients of GJD in managing primary hypertension are puerarin, tanshinone IIA, daidzein, ursolic acid, and cryptotanshinone, which are mainly expected to contain a regulatory function in conjunction with AGTR1, AKT1, EDNRA, MAPK14, MAPK8, and CHRM2." (PMID 36046450, 2022).
fungal infection (2 papers, 2024 to 2025). "Malfunction of AKT1 channels impairs plant growth and reduces resistance to fungal infection." (PMID 40203070, 2025).
hemorrhage (2 papers, 2009 to 2023). Loss of blood from the vascular compartment to the exterior or into nonvascular body space as a result of rupture or severance of the blood vessels. "At 7 days after induction of experimental ICH, 2×105 cells/2 μl of F3 or F3.Akt1 hNSCs were transplanted into ICH mouse cerebral cortex overlying hemorrhage lesion site, 2 mm cranial to the hemorrhagic lesion." (PMID 19440551, 2009).
hypertensive heart disease (2 papers, 2017 to 2025). Abnormal enlargement of the heart resulting from long-standing hypertension. "Akt1 is also linked to cardiac fibrosis by promoting inflammatory response in early stages of hypertensive heart disease." (PMID 28991210, 2017).
invasive lobular breast carcinoma (2 papers, 2025). An infiltrating lobular adenocarcinoma of the breast. "Comparable patterns have been identified in other malignancies, including invasive lobular breast carcinoma, where actionable mutations in AKT1, HER2, and HER3 are prevalent." (PMID 41291320, 2025).
latent infection (2 papers, 2016 to 2023). "The cell proliferation marker MKI67 as well as genes involved in G1-S and G2-M transition, such as CDK1, CDK2, CCNE2, PRIM2, AKT1, and FOXM1, were significantly downregulated in latent infection compared to actively infected cells." (PMID 38038477, 2023).
ovarian adenocarcinoma (2 papers, 2023 to 2025). An adenocarcinoma that arises from the ovary. "Treatment with CUR alone significantly inhibited the growth of human ovarian adenocarcinoma SKOV-3/CDDP CDDP-resistant subline cells by inhibition the gene expression of the antioxidant enzymes (SOD1, SOD2, GPX1, CAT, and HO1), transcription factor NFE2L2 and signaling pathway (PIK3CA/AKT1/MTOR)." (PMID 39859517, 2025).
ovarian granulosa cell tumor (2 papers, 2016 to 2020). A granulosa-stromal cell tumor that arises from the ovary. "Our previous study showed that FHL2 plays a critical role in the initiation and progression of ovarian granulosa cell tumor via regulating AKT1 transcription." (PMID 33092075, 2020). "Our previous study showed that FHL2 plays a critical role in the initiation and progression of ovarian granulosa cell tumor (GCT) via controlling AKT1 gene transcription." (PMID 33092075, 2020).
pediatric cancer (2 papers, 2016 to 2024). "Capivasertib induced objective responses as a single agent in 20 % to 30 % of patients whose cancer had an AKT1 E17K mutation, a mutation that is exceptionally uncommon in pediatric cancers (St." (PMID 39510293, 2024).
pneumocytoma (2 papers, 2022). "In addition, point mutations of AKT1 and internal tandem repeats of AKT1 have been observed in a study of sclerosing pneumocytoma, suggesting that AKT1 mutations are a genetic marker of sclerosing pneumocytoma." (PMID 35341150, 2022). "AKT1 mutation was the most commonly reported gene mutation and was speculated to be the genetic hallmark of sclerosing pneumocytoma." (PMID 35490241, 2022). "Mutations in other tumor-related genes were also identified in the sclerosing pneumocytoma, like PTEN, BRAF V600E, BLM, KMT2D, but with relatively smaller incidence than AKT1 and β-catenin." (PMID 35490241, 2022).
prion disease (2 papers, 2021 to 2026). A transmissible disease that is caused by a protein that is able to induce abnormal folding of normal cellular proteins, leading to characteristic spongiform brain changes, which are associated with neuronal loss without an inflammatory response. "AD pathways involve (IL6, AKT1 and IL1B); prion disease involves (IL6 and IL1B); and pathways of neurodegeneration-multiple diseases involve (IL6, AKT1 and IL1B)." (PMID 41601963, 2026).
PTEN hamartoma tumor syndrome (2 papers, 2022 to 2025). An autosomal dominant syndrome caused by pathogenic variants in the PTEN gene, characterized by hamartomas, overgrowth, neurodevelopmental disorders and an increased risk of various cancers, including breast, thyroid, and endometrial cancer. "PTEN hamartoma tumor syndrome (PHTS) is a rare autosomal dominant syndrome with an estimated prevalence of ~ 1:200,000, caused by germline inactivating mutations or deletions in the PTEN tumor suppressor gene (10q23.31) or in other functionally related genes (e.g., PIK3CA, AKT1)." (PMID 40111709, 2025).
respiratory failure (2 papers, 2009 to 2020). The significant impairment of gas exchange within the lungs resulting in hypoxia, hypercarbia, or both, to the extent that organ tissue perfusion is severely compromised. "Murine knock-outs of the PI3K genes result in embryonic lethality, and double AKT-1 and -2 knock-out animals die within a few hours of birth from respiratory failure, indicating a critical role of PI3K/AKT signaling in lung function and tissue homeostasis." (PMID 19416348, 2009).
retinal (2 papers, 2023 to 2026). "Our previous study showed that the reduction in Akt1 activity in RPE contributes to the retinal vascular lesions in diabetic mice, but whether the increased Akt2 activity in DR RPE impacts disease pathology (progression) has not been investigated." (PMID 37443129, 2023).
rosacea (2 papers, 2023 to 2025). A chronic erythematous skin disorder that affects the face. "Finally, drug–target prediction and molecular docking revealed that AKT1/MAPK1/MMP9 could be the pharmacological targets of EGCG in rosacea." (PMID 36937834, 2023).
scoliosis (2 papers, 2020 to 2025). A congenital or acquired spinal deformity characterized by lateral curvature of the spine. "A 10-year-and-3-month-old patient with PS caused by an serine/threonine protein kinase 1 (AKT1) gene mutation, who was referred to our hospital for bilateral lower extremity weakness following scoliosis surgery." (PMID 41261675, 2025).
soft tissue tumors (2 papers, 2017 to 2020). "Although Akt1 overexpression was prominent in soft tissue tumours, it was still lower than that of Akt2 or Akt3." (PMID 28209968, 2017).
sudden cardiac arrest (2 papers, 2019 to 2021). Unexpected rapid natural death due to cardiovascular collapse within one hour of initial symptoms. "Taken together, drugs that target Akt1 and its effectors may have the potential to mimic hypothermia-like protection to improve sudden cardiac arrest survival when administered during CPR." (PMID 31398213, 2019).
systemic sclerosis (2 papers, 2021 to 2024). A chronic disorder, possibly autoimmune, marked by excessive production of collagen which results in hardening and thickening of body tissues. "AKT1 is reported to be a strong regulator of ACTA2 in fibroblasts freshly isolated from skin with systemic sclerosis." (PMID 33799788, 2021).
acute endometritis (1 paper, 2024). An acute, usually bacterial infection affecting the endometrium. "Endometrial inflammation during LPS-induced acute endometritis significantly upregulated Col1a1 and Akt1 gene expression in mouse uterine tissues (p < 0.01), whereas leonurine was able to significantly reduce the inflammation-induced increase in Col1a1 and Akt1 gene expression." (PMID 39062636, 2024).
acute pharyngitis (1 paper, 2024). An acute and painful inflammatory process that affects the pharynx. "Our initial exploration revealed that TR treatment for acute pharyngitis engages targets such as PIK3CA, IL6, AKT1, TNF, PTGS2/COX-2, among others." (PMID 39568590, 2024).
aggressive (1 paper, 2012).
anal tumour (1 paper, 2020). "In this regard, it is worth noting that BAY 1125976, a selective allosteric AKT1/2inhibitor, exhibits high efficacy in AKT signalling-dependent breast, prostate and anal tumour growth in mouse models." (PMID 32098189, 2020).
anaplastic glioma (1 paper, 2019). "The stable knockdown of circ-AKT3 in SW1783 cells and in Hs683 anaplastic glioma cells only reduced AKT3-174aa expression, instead of reducing that of AKT1, AKT2 and AKT3." (PMID 31470874, 2019).
benign meningioma (1 paper, 2016). A grade I, slowly growing meningioma. "On the basis of recent whole genome-sequencing approaches, novel candidates in benign meningiomas have been identified which include: TRAF7 (the receptor-associated factor 7), KLF4 (Kruppel-like factor 4), AKT1 (v-akt murine thymoma viral oncogene homolog 1) and SMO (Smoothened)." (PMID 27429002, 2016).
brain inflammation (1 paper, 2018). "We treated AKT1 overexpressing larvae with the immunosuppressant Dexamethasone (DEX) which has previously been shown to inhibit macrophages and microglia upon spinal cord injury and brain inflammation in zebrafish." (PMID 29465400, 2018).
cervical dysplasia (1 paper, 2021). "Besides, multiple megalin-positive cells expressed phosphorylated Akt1, implying that MT- and/or megalin-dependent prosurvival signal transduction pathways might contribute to the development of severe cervical dysplasia." (PMID 33084977, 2021).
cervical small cell carcinoma (1 paper, 2020). A small cell carcinoma arising from the cervix. "Moreover, dynamic monitoring of circulating tumor DNA (ctDNA) showed that the mutation rate of AKT1 E17K in peripheral blood increased successively and was correlated with tumor growth, suggesting that the mutation was a possible molecular mechanism underlying HPD in cervical small cell carcinoma." (PMID 32997401, 2020).
Chronic colitis (1 paper, 2025). A chronic inflammatory disease of the large intestine (colon, cecum and rectum). "Specifically, this heterodimer has been shown to promote macrophage infiltration into colonic tissue and activate the Akt1–Smad5–Id3 signaling axis, ultimately facilitating tumor formation in the context of chronic colitis." (PMID 40565156, 2025).
congenital heart disease (1 paper, 2019). A heart disease that is present at birth. "Among these genes, AKT1, PDPK1, CDC42, AKT3, and PIK3CA have concrete evidences shown in relation with congenital heart disease; even two of them (AKT1, CDC42) have explicit association with VSD." (PMID 31440271, 2019).
cryptosporidiosis (1 paper, 2024). Intestinal infection with organisms of the genus Cryptosporidium. "First, we performed a target database search to obtain a total of 47 intersecting targets of oxymatrine for the treatment of cryptosporidiosis, including the core targets of ALB, IL-6, TNF, AKT1, CASP3, and SRC." (PMID 38914662, 2024). "In order to investigate the mechanism of oxymatrine in treating cryptosporidiosis, we constructed a target-KEGG network and identified the top 5 involved genes, namely RELA, AKT1, TNF, CASP3, and IL-6." (PMID 38914662, 2024).
cylindromas (1 paper, 2019). "The AKT1 mutations may confer lung tissue tropism for cylindromas." (PMID 31624251, 2019).
dermatomyositis (1 paper, 2026). Dermatomyositis (DM) is a type of idiopathic inflammatory myopathy characterized by evocative skin lesions and symmetrical proximal muscle weakness. "Network toxicology analysis suggested that BPA may influence the progression of dermatomyositis by regulating key factors such as AKT1, BCL2, MMP9, ESR1, and INS, thereby affecting apoptosis, immune-inflammatory responses, pathways in cancer, and the PI3K-Akt signaling pathway." (PMID 41911226, 2026).
diabetic foot ulcer (1 paper, 2025). "Among them, quercetin showed the strongest binding affinity with AKT1, with a minimum binding energy of −10.3 kcal/mol, indicating that this compound–target interaction may play a central role in the pharmacological mechanism of Fespixon cream for diabetic foot ulcer treatment." (PMID 40728954, 2025).
ectodermal dysplasia syndrome (1 paper, 2019). "Moreover, mice expressing a permanently activated Akt1 develop alterations in ectodermal organs that are similar to defects present in mice resembling human ectodermal dysplasia syndromes." (PMID 31789342, 2019).
endometrioid cancer of the ovary (1 paper, 2017). "Among these patients, only 2 obtained a PR (one endometrioid cancer of the ovary and one cervical cancer with either PIK3CA or AKT1 mutation) and one got a SD (endometrioid cancer of the ovary with PIK3CA mutations)." (PMID 28008141, 2017).
Fibrous Meningioma (1 paper, 2025). A WHO grade I meningioma characterized by the presence of spindle cells that form bundles in a collagen matrix. "It is well established that fibrous meningiomas commonly harbor NF2 mutations or chromosomal loss, whereas meningothelial tumors frequently carry TRAF7 and AKT1 mutations." (PMID 41154381, 2025).
genital warts (1 paper, 2012). "Loss of AKT1 in non-genital warts causes changes in cornified envelope structure that we postulate are required for HPV virions to escape from the cornified envelope." (PMID 22685591, 2012). "AKT1 expression was lost in 88% of non-genital warts while in this study AKT1 was lost in 42% of VIN." (PMID 22685591, 2012).
gliosarcoma (1 paper, 2021). A rare histological variant of glioblastoma (WHO grade IV) characterized by a biphasic tissue pattern with alternating areas displaying glial and mesenchymal differentiation (WHO).
goiter (1 paper, 2020). Enlargement of the thyroid gland usually caused by lack of iodine in the diet, hyperthyroidism, or thyroid nodules. "We previously showed that PVPV-Akt1WT mice developed goiters beginning at three months of age and deletion of Akt1 reduces thyroid enlargement." (PMID 33110146, 2020).
graft versus host disease (1 paper, 2025). An immune system disorder that occurs after allogeneic hematopoietic stem cell transplant and is a reaction of donor immune cells against host tissues. "AKT1 was involved in allograft rejection, antigen processing and presentation, graft-versus-host disease, neuroactive ligand-receptor interaction, olfactory transduction, and steroid hormone biosynthesis." (PMID 40574839, 2025).
Granuloma (1 paper, 2024). A compact, organized collection of mature mononuclear phagocytes, which may be but is not necessarily accompanied by accessory features such as necrosis. "The PI3K/AKT1 pathway has also been implicated in activation of mTOR, which has been associated with granuloma formation." (PMID 39080656, 2024).
hemangioblastoma (1 paper, 2020). "One patient from this group (F14) without either TRAF7, KLF4, or AKT1 mutations harbored a germline VHL mutation with VHL copy number loss in the tumor, and developed posterior fossa chordoid meningioma followed by hemangioblastoma 12 years later." (PMID 31963394, 2020).
hidradenocarcinoma (1 paper, 2012). A carcinoma with apocrine and less often eccrine differentiation, arising from the sweat glands. "AKT-1 (E17K) mutation was detected in one hidradenocarcinoma." (PMID 23056620, 2012).
Hypercholesterolemia (1 paper, 2024). An increased concentration of cholesterol in the blood. "Treatment of radioresistant cells with statins, drugs used worldwide for the treatment of hypercholesterolemia, significantly attenuated the Akt1/Cav1 signaling and radioresistance mechanisms through increased cell apoptosis." (PMID 38473215, 2024).
Hypokalemia (1 paper, 2025). An abnormally decreased potassium concentration in the blood. "For example, hypokalemia stress may trigger cytoplasmic calcium signaling, which activates CIPK23 via CBL1 and CBL9, and subsequently phosphorylates and activates the potassium channel AKT1." (PMID 40733455, 2025).
intracranial meningioma (1 paper, 2022). A meningioma that arises within the cranial cavity. "In contrast to AKT1-mutant intracranial meningiomas, where TRAF7 mutations are found to co-occur very frequently, we observed only a single AKT1-mutant SM case with a TRAF7 co-mutation." (PMID 35943573, 2022).
intraductal papillary mucinous neoplasm (1 paper, 2024).